OTX2 (orthodenticle homeobox 2)
Diseases named in the same sentence as OTX2 in open-access papers (continued):
Sharing a sentence is not in itself a finding about the gene and the disease.
medulloblastoma (continued). "As MYC, another oncogene is also overexpressed in Group 3 medulloblastoma, OTX2 may promote tumorigenesis by cooperatively binding with MYC to target genes." (PMID 35546872, 2022). "Furthermore, tumours dramatically regressed in these mice leaving only medulloblastoma remnants in external position at 18 months, indicating that Otx2 ablation was sufficient to counteract SmoM2 mitogenic activity and long-term tumour maintenance." (PMID 30100614, 2018). "This might explain why amplification and/or overexpression of Otx2 need to be selected, together with other genetic alterations, to ensure sustained proliferation of Shh-independent medulloblastomas." (PMID 30100614, 2018). "OTX2 is also involved in inhibiting the differentiation of medulloblastoma cells." (PMID 28861107, 2017). "Furthermore, OTX2 has been shown to directly upregulate the expression of c-MYC in medulloblastoma via cis-regulatory elements in the MYC promoter region." (PMID 29124525, 2017). "Interestingly, Otx2 is required for such a “poised” state of histone modifications of target promoters in medulloblastoma cells." (PMID 28620275, 2017). "Besides, ATRA is able to inhibit MB cell growth by suppression of the OTX2 (orthodenticle homeobox 2) gene, which is overexpressed in the majority of medulloblastomas." (PMID 27317342, 2016). "Medulloblastomas originate from deregulated NC cells, and OTX2 is frequently overexpressed in this cancer via gene amplification, where it activates cell cycle genes and inhibits differentiation, illustrating its function as an oncogene with respect to the NPBR." (PMID 26406991, 2015). "Finally, we investigated datasets characterizing the epigenome of various relevant central nervous system (CNS) tissues to draw parallels between OTX2 regulation in medulloblastoma and in the developing brain." (PMID 25198066, 2014). "Moreover, OTX2 is a known oncogenic driver in medulloblastoma, a condition that was diagnosed in the proband during the course of the study." (PMID 24816892, 2014). "The existence of medulloblastomas that lack both OTX2 expression and promoter methylation indicates that DNA methylation is unlikely the initiator of OTX2 repression during development, but rather serves as reinforcement of a repressive chromatin state, as previously demonstrated for other loci." (PMID 25198066, 2014). "However, given that OTX2 itself is required for activation of the key DHS 4 enhancer in medulloblastoma, it would be unlikely for OTX2 to be transcriptionally re-activated through this enhancer in the absence of OTX2 protein." (PMID 25198066, 2014). "Considering that DHS 4 exhibited specific and consistent activity in OTX2-expressing medulloblastoma cells, we reasoned that the activity of trans-acting factors binding to this element may determine the transcriptional status of OTX2 in medulloblastoma." (PMID 25198066, 2014). "Little is known about the mechanisms of OTX2 overexpression in medulloblastoma." (PMID 25198066, 2014). "OTX2 is expressed in the presumptive hindbrain, the tissue from which medulloblastoma arises, and here we have revealed parallels between regulatory element activities in medulloblastoma and corresponding histone modifications in the developing brain." (PMID 25198066, 2014). "The transcriptional regulation of OTX2 in medulloblastoma may thus reflect the regulatory landscape sustained from a particular developmental timepoint or rather an unrelated regulatory mechanism unique to this tumor type." (PMID 25198066, 2014). "The same difference in sensitivity of Daoy and D283 Med cell lines to the ATRA was already described and the higher sensitivity of D283 Med cells is explained by expression of OTX2, a transcription factor, which was reported as a suppressor of neuronal differentiation in medulloblastoma cells." (PMID 24959102, 2014).
medulloblastoma (continued). "Here we have utilized an integrated approach of genomewide regulatory element mapping via DNase-seq followed by conventional reporter assays and transcription factor binding site discovery to characterize the transcriptional regulation of the medulloblastoma oncogene Orthodenticle Homeobox 2 (OTX2)." (PMID 25198066, 2014). "Retinoids are known to repress Otx2 during anterior-posterior embryonic patterning and when added to cultured medulloblastoma cells, and thus have been considered a potential therapeutic agent for medulloblastoma." (PMID 25198066, 2014). "Additionally, OTX2 protein directly activates the only OTX2 regulatory element that is specifically active in OTX2-expressing medulloblastomas." (PMID 25198066, 2014). "Finally, OTX2 enhancers in medulloblastoma are marked by activating histone modifications in the embryonic brain." (PMID 25198066, 2014). "The mechanisms of developmental OTX2 repression that may fail during medulloblastoma tumorigenesis are currently unclear." (PMID 25198066, 2014). "The role of Otx2 in the initiation of medulloblastoma is less clear; however, its uniform expression pattern among non-Shh tumors suggests that Otx2 expression may be acquired during clonal expansion of a preneoplastic lesion." (PMID 22558385, 2012). "Although Otx2-induced hyperplasias share many characteristics of medulloblastoma precursor cells, it is yet to be determined whether these ectopia are indeed preneoplastic lesions." (PMID 22558385, 2012). "This selective growth advantage conferred upon normal hindbrain cell types by Otx2 reveals the potential for this gene to contribute to early stages of medulloblastoma tumorigenesis by altering the spatiotemporal dynamics of neuronal progenitor cell proliferation." (PMID 22558385, 2012). "Indeed, we and others have shown a dependency on OTX2 for medulloblastoma cells with OTX2 expression." (PMID 22016811, 2011). "However, the malignant childhood brain tumor medulloblastoma, which originates in the cerebellum, often expresses OTX2 at high levels." (PMID 22016811, 2011). "As these genes are highly expressed in medulloblastoma, they may also interact with OTX2 to regulate gene expression." (PMID 22016811, 2011). "Together, these data pinpoint, for the first time, a crucial Shh-independent role for Otx2 in the control of proliferation of normal and tumoral granule cell precursors in vivo and make it an attractive candidate for targeted therapy in Shh-dependent medulloblastomas." (PMID 30100614, 2018). "Thus, failure to repress OTX2 during development could be the critical determinant of OTX2 expression status in medulloblastoma." (PMID 25198066, 2014). "Could OTX2 expression be inherited from the medulloblastoma cell of origin?" (PMID 25198066, 2014). "Thus, MEIS2 might be necessary to specify the binding and/or biological function of OTX2 in medulloblastoma." (PMID 22016811, 2011). "For example, a medulloblastoma organoid model was established by overexpressing OTX2 and MYC in human cerebellar organoids to replicate the features of medulloblastoma group 3 tumors." (PMID 38353122, 2024). "For the medulloblastoma data, scMSGL efficiently captured the significant roles that key oncology markers MYC and OTX2 play in the transcriptional regulation of metabolic genes." (PMID 37016281, 2023). "The main tumor in which OTX genes have been studied is medulloblastoma (MB), the most common brain tumor in children, with virtually all medulloblastomas expressing OTX1, OTX2, or both genes." (PMID 38069286, 2023). "The aim of this work was to investigate the physiological function of Otx2 in regulating GCP proliferation and tumorigenesis in the context of normal cerebellum development or type 2 medulloblastoma formation." (PMID 30100614, 2018). "The authors suggested a role for OTX2 dosage sensitivity in human craniofacial development and raised the possibility of a shared etiology between a subtype of HFM and medulloblastoma." (PMID 29311971, 2017).
medulloblastoma (continued). "SHH-activated medulloblastomas express specific target proteins such as p75NGFR and Gab1, share expression of nuclear Yap1 with the WNT medulloblastoma, but lack Otx2 expression." (PMID 27781424, 2016). "OTX2 has recently been shown to repress differentiation, increase proliferation, and upregulate c-MYC in medulloblastoma cells." (PMID 27775567, 2016). "OTX2 transcriptionally regulates cell cycle genes and the MYC oncogene, thereby contributing to medulloblastoma maintenance, and additionally can alter the dynamics of hindbrain progenitor cell migration and proliferation." (PMID 25198066, 2014). "Proposed mechanisms for the oncogenic function of Otx2 include transactivation of cell cycle genes and induction of the MYC oncogene, which seems to play a key role in tumor maintenance in some medulloblastomas." (PMID 22558385, 2012). "In this study, we have analyzed the binding of OTX2 to promoter regions in the complete genome and compared the OTX2 data with ChIP-on-chip data for MYC in medulloblastoma." (PMID 22016811, 2011). "For OTX2, TAATCC, TAAGCC and TAATCT are the most enriched binding motifs in medulloblastoma, in accordance with literature." (PMID 22016811, 2011). "Both OTX2 and MYC are important oncogenes in medulloblastoma, the most common malignant brain tumor in childhood." (PMID 22016811, 2011). "Our data suggest an important functional interaction between OTX2 and MYC in regulating gene expression in medulloblastoma." (PMID 22016811, 2011). "Together these results suggest that OTX2 and MYC cooperate in regulating gene expression in medulloblastoma." (PMID 22016811, 2011). "We found the same correlation between OTX2/MYC binding and gene expression when we used expression data of medulloblastoma tumors." (PMID 22016811, 2011). "For medulloblastoma, another embryonal tumor originating in the cerebellum, an oncogenic role with overexpression of OTX2 was shown mainly in non-WNT/non-SHH medulloblastomas." (PMID 41291966, 2025). "Notably, 37 of the superenhancers had known Group 3 and 4 medulloblastoma drivers as their nearest genes, including CHD7, CBFA2T2, GSE1, and of course, OTX2, and ZIC1." (PMID 41279093, 2025). "Werbowetski-Ogilvie, Taylor and colleagues report a noncanonical role for OTX2 in regulating alternative splicing and controlling a stem cell and pro-tumorigenic splicing program in group 3 medulloblastoma." (PMID 39025928, 2024). "In fact, pharmacologically relevant doses of ATRA induce apoptosis in medulloblastoma cells—although no connection with anaplastic histology or inhibition of OTX2 expression was established." (PMID 38069286, 2023). "While mice overexpressing the gene combinations GFI1 + c-MYC (GM) and OTX2 + c-MYC (OM) induced brain tumors, only the latter combination developed medulloblastoma clustered with Group 3 subtype, highlighting the role of OTX2 and c-MYC as the medulloblastoma driver genes." (PMID 36831595, 2023). "Conversely, one would expect that in other types of medulloblastoma with granule precursor as the cell of origin, but where the Shh pathway is not deregulated, proliferation would mostly rely on the Otx2 alternative pathway." (PMID 30100614, 2018). "Together, these results indicate that Otx2 is not required to initiate medulloblastoma formation in Otx2+ granule cell precursors under constitutive SmoM2 stimulation." (PMID 30100614, 2018). "Intriguingly, in contrast to group 3 and group 4 medulloblastomas, overexpression and focal gain of OTX2 are usually not observed in type 2 tumours, where the Shh pathway is overactivated, even though this subtype is known to originate from GCPs14,15,19,21,22." (PMID 30100614, 2018). "This has led to the current view that Otx2 is not relevant in the tumorigenesis of Shh-medulloblastomas, although this has never been formally demonstrated." (PMID 30100614, 2018).
medulloblastoma (continued). "Non-WNT/non-SHH medulloblastomas finally express Otx2 but lack the other markers such as Yap1 (which is only expressed in endothelial cells in this tumor type serving as internal control and nuclear β-catenin." (PMID 27781424, 2016). "Our previous studies have revealed the importance of the homeobox transcription factor OTX2 to the maintenance of non-Shh medulloblastomas." (PMID 25198066, 2014). "DNase-seq analysis of ES cells, which appear to express OTX2 from the short isoform promoter revealed shared proximal DHS sites with medulloblastoma but lack of DNase hypersensitivity at medulloblastoma DHS sites 1–4." (PMID 25198066, 2014). "In order to map the transcriptional regulatory elements of the OTX2 gene, we performed DNase-seq on two medulloblastoma cell lines, D341 and D721, which overexpress OTX2 independent of genomic copy number gain." (PMID 25198066, 2014). "Of the 42 highly-scoring transcription factors, none were expressed consistently in OTX2-expressing medulloblastomas as detected by SAGE, with the sole exception of OTX2 itself." (PMID 25198066, 2014). "We identified variable promoter activities of DHS sites 6 and 7 among medulloblastoma cell lines, indicative of a role for tumor genetic background (independent of OTX2 status) in affecting proximal regulatory element utilization in this tumor." (PMID 25198066, 2014). "In contrast, ectopic OTX2 did not enhance endogenous OTX2 expression in medulloblastoma cells that do not normally express OTX2, indicating that the appropriate cellular context is required for OTX2 autoregulation." (PMID 25198066, 2014). "This work thus establishes a basis for future studies characterizing the pathogenesis of non-Shh/non-Wnt medulloblastomas in relation to the phenotypes induced by Otx2 described herein." (PMID 22558385, 2012). "We previously reported that medulloblastomas lacking expression of the OTX2 oncogene are preferentially of desmoplastic histology and diagnosed in very young children and adults." (PMID 18769486, 2008). "Why is human Shh medulloblastoma the only type that does not show Otx2 overexpression?" (PMID 30100614, 2018). "However, how Otx2 might influence GCP proliferation in vivo during normal cerebellum development and how it might contribute to medulloblastoma formation is currently unknown." (PMID 30100614, 2018). "As expected, these bona-fide type 2 medulloblastomas did not display Otx2 overexpression (Sup." (PMID 30100614, 2018). "Moreover, OTX2 and c-MYC are frequently coexpressed at high levels in medulloblastoma and regulate many of the same genes, indicating there might be a functional interaction between these two genes." (PMID 27775567, 2016). "Furthermore, we have demonstrated that medulloblastoma cells not expressing OTX2 are refractory to OTX2 transcriptional activation through trans-acting factors." (PMID 25198066, 2014). "Thus, OTX2 expression in medulloblastoma requires both positively-acting transcriptional regulators as well as a lack of OTX2 promoter methylation." (PMID 25198066, 2014). "However, this approach is not applicable to specific pathological entities, such as OTX2-expressing medulloblastoma, for which there are limited animal models amenable to transgenic reporter analysis." (PMID 25198066, 2014). "OTX2 (Orthodenticle Homeobox 2) is the most frequent target of focal gain in the medulloblastoma genome, and this event occurs almost exclusively in non-Shh/non-Wnt medulloblastomas." (PMID 22558385, 2012). "Thus, OTX2 seems to have a functional interaction with MYC, which might explain why both genes are frequently co-expressed at high levels in medulloblastoma." (PMID 22016811, 2011). "Interestingly, the oncogene OTX2, which is amplified in a low percentage of medulloblastomas, but highly expressed in about 75% of medulloblastomas, is not or hardly expressed in group B tumors." (PMID 18769486, 2008).
medulloblastoma (continued). "Additionally, their medulloblastoma model showed sensitivity towards tazemetostat, an EZH2 inhibitor, suggesting it may be a potential drug for Group 3 medulloblastoma patients overexpressing OTX2 and c-MYC." (PMID 36831595, 2023). "Both in the developing cerebellum and cerebellar medulloblastoma, OTX2 is highly expressed, and has been shown to possess oncogenic activity in non-WNT/non-SHH medulloblastomas." (PMID 36181537, 2022).
microphthalmia (36 papers, 2007 to 2025). Congenital or developmental anomaly in which the eyeballs are abnormally small. "Heterozygous loss of function mutations in OTX2 on chromosome 14q22 cause a wide variety of ocular anomalies, ranging from anophthalmia/microphthalmia to retinal defects, eventually associated with CNS malformations." (PMID 40038803, 2025). "Incomplete vascularisation of the peripheral retina has been reported in the microphthalmia eyes of a 25-month-old female harbouring the OTX2 variant, c.135dupA, [p.(Thr46AsnfsTer84)]." (PMID 39023660, 2024). "Haploinsufficiency for OTX2 with only a single copy of a coding allele causes microphthalmia in mouse models and rare human cases." (PMID 37181651, 2023). "Both causes microphthalmia with many similar manifestations, suggesting high-level (>50%) OTX2 expression is essential to eye development." (PMID 37181651, 2023). "Heterozygous mutations in OTX2 associated with early-onset retinal dystrophy with atypical maculopathy and bilateral microphthalmos have been reported." (PMID 32111086, 2020). "Single-gene deletions and mutations affecting the ability to produce proteins and enzymes such as SOX2, MFRP, ALDH1A3, STRA6, PAX2, and OTX2, have been identified as causing isolated microphthalmia and anophthalmia and syndromic forms." (PMID 30153864, 2018). "OTX2 mutations are the second most common genetic cause of microphthalmia/anophthalmia (after SOX2); furthermore, the gene is responsible for a very small proportion (less than 1%) of infantile retinal disorders, such as Leber’s congenital amaurosis." (PMID 30268123, 2018). "Among them including Sox2, Otx2, Pax6, have been associated with anophthalmia and microphthalmia in many individuals." (PMID 27494603, 2016). "Other genes have been identified as causing isolated anophthalmia or microphthalmia in humans (orthodenticle homeobox 2 [OTX2], retina and anterior neural fold homeobox [RAX], and CEH10 homeodomain-containing homolog [CHX10])." (PMID 21203406, 2010). "Mutations in OTX2 have been associated with various severe eye malformations, including anophthalmia and microphthalmia." (PMID 19158959, 2009). "OTX2 mutations in humans have been associated with a range of ophthalmological phenotypes including anophthalmia, microphthalmia, developmental anomalies of the optic nerve and chiasm, and Leber congenital amaurosis (LCA)." (PMID 19956411, 2009). "Heterozygous loss-of-function mutations of OTX2 (on chromosome 14q22, autosomal dominant inheritance) have been shown to be associated with a wide range of ocular disorders from anophthalmia and microphthalmia to retinal defects." (PMID 18039390, 2007). "OTX2 disease-causing variants are more commonly known for anophthalmia, microphthalmia, anterior segment dysgenesis, optic nerve dysplasia/hypoplasia and combined pituitary hormone deficiency, with an overall estimated frequency of ocular anomalies as high as 86%." (PMID 39023660, 2024). "Moreover, this current mutation model resembles the clinical manifestations of human mutations of OTX2 that lead to different degrees of microphthalmia and anophthalmia more than any other reported model of OTX2 ablation." (PMID 32347797, 2020). "Deletions of the 14q22-q23 region, which includes BMP4 as well as OTX2, also known to be important for eye development, have been described causing anophthalmia/microphthalmia and also hearing problems, Pierre-Robin sequence, developmental delay and cleft palate." (PMID 30568244, 2019). "Accordingly, Otx2 was previously related to vertebrate brain and retinal development, and phenotypes that have been associated with heterozygous Otx2 mutations and whole deletion mutations include anophthalmia, microphthalmia and retinal dystrophy." (PMID 30718229, 2019).